GPX1 (glutathione peroxidase 1)
Diseases named in the same sentence as GPX1 in open-access papers (continued):
Sharing a sentence is not in itself a finding about the gene and the disease.
breast carcinoma (55 papers, 2006 to 2025). "In accordance with our results, the GG genotype was associated with a higher risk of breast cancer and with higher detoxification activity due to higher GPX1 activity in these individuals." (PMID 40565143, 2025). "They proposed that the GPX1 variant Leu-allele has a protective effect against breast cancer, and Pro198Leu polymorphism is significantly associated with breast cancer risk via affecting oxidative stress." (PMID 35626163, 2022). "Loss of heterozygosity in the GPX-1 gene is a common event in breast cancer, as well as in other cancers, and suggests an important role for GPX-1 in cell homeostasis." (PMID 35215475, 2022). "Our findings support a lower risk of breast cancer for women with the SNP rs1050450 T/T in GPX-1, and a protective effect of dietary intake of selenium among these women." (PMID 35215475, 2022). "Several researchers expressed GPX1 protein encoded by allelic variants in human lymphoblast and breast cancer cell lines and found that alleles expressing Pro198Leu and Ala7 polymorphisms were more cytoplasmically located than other alleles." (PMID 35626163, 2022). "The two main findings in this study were that rs1050450 in GPX-1 is associated with decreased risk of breast cancer for T/T carriers, and modifies the effect of dietary selenium intake on breast cancer risk." (PMID 35215475, 2022). "It was discovered that the leucine-containing allele was more frequently associated with breast cancer than the proline-containing allele and with lower GPX1 enzyme activity to selenium-mediated stimulation." (PMID 35626163, 2022). "As expected, compared to those healthy control subjects, the tissues of breast cancer patients exhibit significantly increased lipid peroxidation, which is dependent on functional polymorphism of GPx1." (PMID 32571353, 2020). "GPx1 gene P198L polymorphism has been reported to be related with some oxidative stress-related diseases, such as lung cancer, breast cancer, bladder cancer, diabetic peripheral neuropathy, and inflammatory bowel disease." (PMID 31781040, 2019). "(2010) showing that combination MnSOD Ala9Val and GPX1 Pro198Leu genotypes were found to have a 1.6 times higher risk of sporadic breast cancer as compared to the control group." (PMID 29411539, 2018). "The corner stone of this case–control study is to assess the GPX1 Pro198Leu polymorphism status in Rwanda and to evaluate the association between this polymorphism and breast cancer development among Rwandan patients." (PMID 29411539, 2018). "Genomic DNA from peripheral blood leukocytes of 41 patients with breast cancer and 42 healthy controls were enrolled and genotyped GPX1 Pro198Leu polymorphism by PCR amplification and DNA sequencing." (PMID 29411539, 2018). "Leu allele for GPX1 rs1050450 was associated with decrease in eGPx activity and increase of breast cancer risk in a Danish population." (PMID 27164132, 2016). "Breast cancer risk was significantly associated with GPX1 rs1050450 (Pro198Leu) polymorphism, showing a protective effect of variant (Leu) allele." (PMID 26446998, 2015). "The results of earlier case control studies on breast cancer risk and GPX1 rs1050450 polymorphism are also inconsistent between each other, showing lack of any associations or the increased risk linked to the carriage of the variant allele." (PMID 26446998, 2015). "In a recent study by Meplan, GPX1 rs1050450 was shown to interact with hormone therapy to alter risk of breast cancer." (PMID 24278290, 2013). "For instance, individuals with certain variants of GPX1 (e.g., Pro198Leu) may exhibit altered enzyme activity and reduced antioxidant defense, potentially modifying their susceptibility to breast cancer in response to selenium intake." (PMID 40901095, 2025). "Interestingly, NME7 has been recognized for its tumor-suppressive role in breast cancer, whereas GPX1 is linked to the regulation of tumor metastasis." (PMID 39664386, 2024).
breast carcinoma (continued). "However, our results are in agreement with the results obtained in a study conducted on patients with breast cancer, showing a protective effect of the GPX1-Leu allele." (PMID 36676755, 2023). "GPx belongs to a group of stress-related selenoproteins, and since GPx-1 allelic identity is associated with breast cancer development, decreased tumor growth was expected to be associated with increased hepatic GPx activity in the Se-Nuts group compared to the control group." (PMID 36634075, 2023). "As with breast cancer, there is disagreement about whether GPX1 polymorphism is associated with bladder cancer susceptibility." (PMID 35626163, 2022). "A recently published study demonstrated, using the IHC approach, that high expression levels of GPX1 were associated with shorter overall survival and higher mortality rates in breast cancer patients and played a vital role in the metastasis of TNBC cells by regulating cell adhesion." (PMID 35158912, 2022). "Gpx1 (glutathione peroxidase 1) encodes for a cytosolic antioxidant enzyme important for modulating reactive oxygen species in the tumor microenvironment that is elevated in M2-polarized TAMs in breast cancer." (PMID 34743736, 2021). "Similarly, in breast cancer, LOH at this locus occurred in approximately 36% of breast cancer tissues, and GPx1 with a leucine-containing allele exhibited lower GPx1 activities in response to stimulation than GPx1 a proline-containing allele." (PMID 32571353, 2020). "Artificial overexpression of GPx1 showed an increased capacity to rescue breast cancer cells from the cell cycle arrest caused by hyperoxic stress, indicating the involvement of both peroxide-derived free radicals and nonperoxide-derived species during the deleterious process." (PMID 32571353, 2020). "(2010) indicated the existence of significant ethnic variation in the GPX1 Pro198Leu polymorphism and breast cancer development and suggested that the polymorphic variant may increase the risk only among Africans." (PMID 29411539, 2018). "The present case–control study was planned to assess the presence of GPX1 Pro198Leu polymorphism in Rwanda population to determine whether it is associated with the risk of developing breast cancer." (PMID 29411539, 2018). "GPX1 polymorphism may be an important factor modifying oxidative stress response in breast cancer subjects." (PMID 26446998, 2015). "Breast cancer risk was significantly associated with GPX1 rs1050450 polymorphism in this study." (PMID 26446998, 2015). "The results of this study suggest that GPX1 polymorphism may be an important factor that modifies oxidative stress response in breast cancer." (PMID 26446998, 2015). "In breast cancer patients, high expression of GPx1 was associated with high rate of patient mortality and shorter overall survival, which may be due to NF-κB." (PMID 26020962, 2015). "This SNP is linked to the amino acid substitution, from proline (Pro) to leucine (Leu), and this change was shown to affect GPx1 activity, with the polymorphic variant (Leu) being less responsive to Se as observed in vitro, in human breast cancer cells (MCF-7)." (PMID 26446998, 2015). "Since lipid peroxidation products have been recently recognized as a therapeutic target in cancer, the possible relationship between lipid peroxidation and GPX1 polymorphism could have a potential role in breast cancer treatment." (PMID 26446998, 2015). "Other studies have indicated that glutathione peroxidases may be associated with breast cancer risk, specifically GPX1, a cytosolic antioxidant." (PMID 24278290, 2013). "In addition to being relevant to cell apoptosis, the upregulation of GPX1 is also associated with chemotherapeutic resistance in breast cancer." (PMID 24280356, 2013). "Polymorphisms in the GPX-1 and MnSOD genes are associated with an increased risk of breast cancer." (PMID 16945136, 2006).
breast carcinoma (continued). "The MYC oncogene is highly expressed in CTCs from metastatic variants of breast cancer, and it regulates the adaptation of CTCs to the brain environment by reducing the oxidative stress produced by activated microglia via gene upregulation of glutathione peroxidase 1 (GPX1)." (PMID 40076927, 2025). "Thus, evaluation of association of GPX1 Pro198Leu polymorphism with breast cancer would be more interesting when combined with other common variation in other polymorphic genes encoding for antioxidant defence enzymes, including MnSOD, in modulating individual susceptibility to breast cancer." (PMID 29411539, 2018). "However, an increased risk of breast cancer was observed in individuals who carry both the Leu198Leu genotype of GPX1 and Ala16Ala genotype of MnSOD which is in favor of a GPX1 and MnSOD interaction responsible of an increased risk of breast cancer development (Cox, Tamimi, & Hunter, 2006)." (PMID 29411539, 2018). "Therefore, we have planned to conduct this case–control study to assess the presence of GPX1 Pro198Leu polymorphism in Rwandan population to determine whether this polymorphism is associated with the risk of developing breast cancer in Rwandan patients." (PMID 29411539, 2018). "Thus it may be speculated that GPX1 polymorphism may affect breast cancer treatment via modulating lipid peroxidation." (PMID 26446998, 2015). "Polymorphisms in selenoprotein genes, such as GPx1 and selenoprotein P (SELENOP), can influence how selenium impacts breast cancer." (PMID 40901095, 2025). "GPX1 and 4 andTXNRD1 and 3 are essential for redox homeostasis and their combined overregulation in TNBC is probably associated with the response of breast cancer cells to increase oxidative stress." (PMID 35158912, 2022). "The levels of SELENBP1 resulted to be down-expressed in the TNBC cells compared to other breast cancer cellular subtypes, confirming the inverse correlation between GPX1 and SELENBP1 levels in TNBC cells." (PMID 35158912, 2022). "GPX1 knockdown promotes apoptosis and reduces the tumorigenic growth of breast cancer cell line MDA-MB-231." (PMID 35626163, 2022). "GPX4, as GPX1, was found to be highly expressed in different cancer tissues, including breast cancer, and also correlated with shorter patient survival." (PMID 35158912, 2022). "GPX1 overexpression in breast cancer cell line T47D can partially inhibit doxorubicin-induced apoptosis by interfering with the sphingomyelin-ceramide pathway." (PMID 35626163, 2022). "Docosahexaenoic acid dietary supplementation increases tumor sensitivity to anthracyclines by reducing cytosolic GPX1 activity in breast cancer cell line MDA-MB-231 and rat mammary tumors, which can be abolished by vitamin E." (PMID 35626163, 2022). "Erastin depletes levels of the antioxidant selenoproteins GPX4 and GPX1 in breast cancer cells by inhibiting xCT-dependent extracellular reduction which is required for selenium uptake and selenocysteine biosynthesis." (PMID 33672555, 2021). "The researchers detailed the molecular partners involved in GPX1-mediated signaling inside cancer cells, and demonstrated that genetically reducing GPX1 expression dramatically reduces tumor growth in a mouse model of breast cancer." (PMID 34158609, 2021). "Although such research is limited, the overexpression of GPx1 in breast cancer is thought to promote the occurrence and development of breast cancer." (PMID 32571353, 2020). "In a breast cancer rodent model, CPA and DOX caused increased expression of oxidative stress related genes such as glutathione peroxidase 1 (GPX1), peroxiredoxin 1 (PRDX1), and NF-ΚB in the hippocampus." (PMID 33352780, 2020). "In addition to the Leu198Leu genotype in the GPx1 gene, the Ala16Ala genotype in the manganese superoxide dismutase (MnSOD) gene, the most significant enzyme that protects against ROS in the human body, was also associated with an increased risk of breast cancer." (PMID 32571353, 2020).
breast carcinoma (continued). "The controversial expression pattern of GPx1 in breast cancers requires further investigation to determine its molecular functions." (PMID 32571353, 2020). "The highlighted genes were also upregulated in clinical samples of lung metastasis from breast cancer patients; (E) IHC analysis of GPX1, an antioxidant gene product identified by Flura-seq to be selectively upregulated in lung micrometastases." (PMID 30912515, 2019). "As compared to the control subjects, lipid peroxidation and GPx1 activity were significantly higher in the breast cancer cases, whereas ceruloplasmin activity was decreased." (PMID 26446998, 2015). "The possible functional significance of the distribution of GPx-1 between the mitochondria and cytoplasm was revealed by a recent study in which GPx-1 allelic variants were exclusively expressed in MCF-7 human breast cancer cells." (PMID 26007340, 2015). "After genotype stratification, both GPx1 activity and TBARS concentration were the highest in GPX1 Pro/Pro homozygotes affected by breast cancer." (PMID 26446998, 2015). "In our study, increased plasma lipid peroxidation in cancer subjects was accompanied by the increased activity of GPx1, supporting other findings on the altered antioxidant homeostasis in breast cancer." (PMID 26446998, 2015). "GPX1 expression was as well silenced by aberrant hyper methylation in ~20% of primary breast cancers." (PMID 25988760, 2015). "For example, GPX1 gene allelic variants and loss of heterozygosity (LOH) at 3p21.3p region contribute to breast cancer development." (PMID 24790704, 2014). "There are five different forms of GPx in humans, however, GPx1 and 4 are more relevant to breast cancer." (PMID 23153283, 2012). "It has been reported that Gpx1 protects against CD95-induced apoptosis in cultured breast cancer cells and inhibits 5-lipoxygenase in blood cells; overexpression delays endothelial cell growth and increases resistance to toxic challenge." (PMID 22216095, 2011). "However, given that both genes act as antioxidants, we hypothesized that being homozygous for the 198Leu allele of GPX-1 which is less responsive to selenium, and the 16Ala allele of MnSOD which is associated with increased urinary DNA adduct levels increases breast cancer risk." (PMID 16945136, 2006). "In 2006, studies by Ravn H showed that carriers with the variant T allele of GPX1 Pro198Leu had a higher risk of breast cancer and decreased GPX1 activity than non-carriers in Danish women using prospectively collected blood samples." (PMID 35626163, 2022). "The interaction between SELENBP1 and GPX1 is found in MCF-7 breast carcinoma cells." (PMID 36386843, 2022). "In MDA-MB-231 breast cancer cells, depletion of GPx1 enhanced only sustained JNK activation." (PMID 34158609, 2021). "The expression of the GPX1 gene was associated with increased drug resistance in various cell lines, including SR16157 (for treating breast cancer), fulvestrant (for treating for breast cancer), and bisacodyl active ingredient (for treating glioblastoma)." (PMID 33706760, 2021). "Increased expression of GPX1 indicated poor prognosis of breast cancer." (PMID 32782436, 2020). "They demonstrated that GPX1 had the ability to respond to ROS to alleviate the tumor progression of breast cancer and supplemental of Se could maintain the activity of GPX." (PMID 32735635, 2020). "The results of this preliminary study showed that 198Leu genotype is rare in Rwanda and suggest that GPX1 Pro198Leu polymorphism is not a risk factor for breast cancer development." (PMID 29411539, 2018). "(2013) have showed that the significant association of GPX1 GPX1 Pro198Leu polymorphism and breast cancer development has been restricted only to the nonductal cancers." (PMID 29411539, 2018). "Interestingly, we observed a positive correlation between plasma TBARS concentration and GPx1 activity measured in blood erythrocytes of the breast cancer subjects." (PMID 26446998, 2015).
breast carcinoma (continued). "Leu carriers for rs1050450 (Pro198Leu) in GPX1 were shown to have a 1.9-fold increased risk of developing non-ductal breast cancer." (PMID 24039907, 2013). "A meta-analysis of six case-control studies of the Pro198Leu polymorphism (rs1050450) in GPX1, did not see an association between breast cancer risk in Caucasians, although they did see a strong increased risk of breast cancer among African women." (PMID 24278290, 2013). "Polymorphisms in the manganese superoxide dismutase (MnSOD) and glutathione peroxidase (GPX-1) genes have been proposed as low penetrance alleles, and have not been clearly associated with breast cancer." (PMID 16945136, 2006). "Therefore, GPX1 may exhibit tumor-promoting activity in breast cancer mainly by regulating cancer cell apoptosis and redox." (PMID 35626163, 2022). "The result of this study suggested that GPX1 Pro198Leu polymorphism could not be a risk factor for breast cancer in Rwanda." (PMID 29411539, 2018). "Previous studies have suggested that the GPX1-200Leu variant has about 10% lower GPX activity than the wild-type enzyme and that the frequency of the Leu allele is strongly associated with the risk of cancer, such as lung cancer, breast cancer, meningioma, and prostate cancer." (PMID 24058403, 2013). "While neither allele alone shows any change in breast cancer risk, an increase in the risk of breast cancer (OR 1.87, 95% CI 1.09 – 3.19) is observed in individuals who carry both the Ala16Ala genotype of MnSOD and the Leu198Leu genotype of GPX-1." (PMID 16945136, 2006). "SELENBP1 regulates GPX1 expression in hepatocellular carcinoma (HCC), breast cancer, colon cancer, and skin cancer." (PMID 36386843, 2022). "Some reports showed that genetic variations in some selenoproteins, such as GPX1, GPX3, GPX4, SELENOS, and TXNRD1, are correlated to breast cancer development." (PMID 35158912, 2022). "The results revealed that GPX1, GPX2, GPX3 and GPX4 protein levels were markedly decreased in breast cancer when compared with normal controls." (PMID 32782436, 2020). "Expressing GPX1 in MCF7 human breast cancer cells that do not exhibit detectable GPX1 levels resulted in a decline in both SBP1 mRNA and protein levels." (PMID 30400135, 2018). "Since we observed that GPx1 deficiency enhanced TNF-α-induced apoptosis of MCF7 (luminal A type and RIPK3-negative) cells, the antiapoptotic function of GPx1 is thought to be independent of the molecular subtype of breast cancer." (PMID 34158609, 2021). "However, the other four GPXs family genes (GPX1, GPX5, GPX6 and GPX7) showed no statistical diagnostic values in breast cancer." (PMID 32782436, 2020). "As the decrease in GPX1 was not at the transcriptional level and previously reported that CUEDC2 promotes the ubiquitination and degradation of the progesterone receptor (PR) and estrogen receptor‐α (ER‐α) in breast cancer cells." (PMID 27286733, 2016). "Overall, considering both the CCLE and LINCS datasets, eight selenoproteins were overexpressed (DIO2, GPX1, GPX4, SELENOI, SELENON, SELENOS, TXNRD1 and TXNRD3) and five were down-expressed (DIO1, GPX2, GPX3, SELENOP and SELENOW) in TNBC compared to all other “non-TNBC” breast cancer subtypes." (PMID 35158912, 2022). "The immortalized lymphocyte cell line GM10832 and breast cancer-derived cell line MDA-MB-231 were each exposed to cytostatic doses of imatinib (300 nm and 500 nM, respectively) for 7 days and no significant change in either GPx activity or GPx-1 protein levels were observed." (PMID 24691473, 2014).